CD4 (CD4 molecule)
Diseases named in the same sentence as CD4 in open-access papers (continued):
Sharing a sentence is not in itself a finding about the gene and the disease.
COVID-19 (continued). "Further assessment and analysis of the SARS-CoV-2-specific T-cell memory at 4 M revealed the enhanced IFNγ+CD4+ and CD8+ memory T cell responses with increasing in the initial COVID-19 severity from mild to moderate to severe." (PMID 38811527, 2024). "CD4 count, CD8 count, and CD4/CD8 ratio were similar between the dose groups at baseline and before COVID-19 (p > 0.05)." (PMID 39772028, 2024). "Our study indicates that PLWH receiving suppressive antiretroviral therapy mount strong CD4+ and CD8+ T-cell responses to COVID-19 vaccines that are comparable to those observed in individuals without HIV." (PMID 38793543, 2024). "A significant decrease in lymphocyte count was observed either in CD8+ cell alone or in both CD4+ and CD8+cells, especially in intensive care unit (ICU) COVID-19 patients." (PMID 38965547, 2024). "Here, we demonstrate that spike-specific CD8+ and CD4+ T cells were boosted by SARS-CoV-2 vaccination, indicating beneficial effects of COVID-19 vaccination in individuals with or recovered from long COVID." (PMID 39284068, 2024). "We observed a transient increase in CD4 count and CD4/CD8 ratio over a two-month window following COVID-19 vaccination, particularly after the second and third doses." (PMID 39772028, 2024). "In the early stages of infection, lymphocytes and lymphocyte subsets (T cells, CD4+, and CD8+ T cell subsets) were significantly lower in patients with severe COVID-19 and severe influenza A than in healthy controls." (PMID 38088542, 2024). "The OR for LAG3 in COVID-19 was 1.46 (95% CI: 1.11–1.92), meaning that patients with LAG3+ CD4+ TEM cells are 1.46 times more likely to develop PTB and COVID-19 infection than patients with LAG3− CD4+ TEM cells." (PMID 39337460, 2024). "The CD4+CD38+ and CD8+CD69+ subsets accurately classified COVID-19 vs. healthy controls throughout the kinetic analysis." (PMID 39597661, 2024). "(H) Violin plots illustrate FCGR3A (CD16) expression intensity on CD4+ and CD8+ T cells, with each dot representing an individual cell in BALF from healthy controls (HCs) and COVID-19 patients, derived from single-cell RNA-seq dataset GSE145926." (PMID 38607373, 2024). "Vaccinated PWH had higher CD4 values, were more recently diagnosed with HIV, had an STI diagnosed in the past 18 months, and had received a COVID-19 vaccine." (PMID 38392862, 2024). "As expected, variable, albeit high frequencies of activated, proliferating and/or exhausted/senescent CD4+ and CD8+ T cells were observed in a large majority of COVID-19 patients at baseline, when compared against values detected in healthy volunteers." (PMID 39896810, 2024). "The numbers of CD4+ and CD8+ cells decreased, accompanied by a sharp rise in the number of exhausted T cell, contributing to the deterioration of COVID-19-related respiratory distress." (PMID 38576608, 2024). "In mild COVID-19, CD8+ resident-memory (TRM) and CD4+ T-helper-17 (TH17) cells undergo active expansion with good effector functions, while in critical cases, they remain more naïve." (PMID 38371516, 2024). "PLWH who are male, older, have low CD4 count, and detectable HIV-VL have reduced occurrence of COVID-19 symptoms." (PMID 39127636, 2024). "Cytotoxic TFH subpopulations with perforin and granzyme B expression have been detected among CD4+ T cells in children with group A Streptococcal recurrent pharyngitis (GAS RT) and in severely ill COVID-19 patients among virus-specific CD4+ T cells." (PMID 39025930, 2024). "This study is one of the few to comprehensively characterize the cross-reactive memory CD4+ and CD8+ T cells in unvaccinated symptomatic and asymptomatic COVID-19 patients." (PMID 38605956, 2024). "Increased numbers of CD4+ TEM cells have been reported in infectious illnesses involving PTB and COVID-19, and this is thought to be a novel observational indicator of clinical diagnosis and outcome." (PMID 39337460, 2024).
COVID-19 (continued). "Using a flow cytometric gating strategy, we examined the frequency of CD3+, CD4+ and CD8+ T, NK cell subsets and NKT cells in the peripheral blood of COVID-19 patients with moderate and severe disease." (PMID 39764446, 2024). "Cross-reactive SARS-CoV-2-specific memory CD4+ and CD8+ T cells are not only present in COVID-19 patients but also in up to 50% of UPPHI." (PMID 38318166, 2024). "The present comprehensive analysis demonstrates, both in vitro and ex vivo, that unvaccinated severely ill COVID-19 patients had higher frequencies of phenotypically and functionally exhausted CCCs/SARS-CoV-2 cross-reactive CD4+ and CD8+ T cells." (PMID 38605956, 2024). "Determine the cellular character of the inflammatory infiltrate in children of different age groups with COVID-19 based on the levels of expression of immunocompetent cell differentiation clusters: CD3, CD4, CD20, CD68, CD163, and CD138." (PMID 38397914, 2024). "COVID-19 vaccine is recommended for PWH, especially those with CD4 count <200 cells/uL, unsuppressed/detectable HIV viral load, or opportunistic infection, who are considered a high-priority group for vaccination." (PMID 39772028, 2024). "At multivariate analysis, factors that predicted mortality included function impairment, CD4 + count ≤ 200 cells/μL, undocumented CD4 + status, address > 20 km from hospital, ART interruption, COVID-19, liver disease and co-infections." (PMID 38388345, 2024). "In mild COVID-19, SARS-CoV-2 induces a memory and Th1 phenotype with CD4+ T cells expressing higher levels of IFN-γ, IL-2 and TNF and a strong response of CD8+ T cells with high expression of granzyme A, B, and perforins." (PMID 39376569, 2024). "An increase in CD3+, CD4+, CD68+, CD163+, and CD20+ CD138+ immunocompetent cells was found in the appendix of children with COVID-19." (PMID 38397914, 2024). "One of the most prominent alteration in the T-cell phenotype herein described is the abnormal accumulation of late differentiated effector CD4+ and CD8+ T cells in COVID-19 patients." (PMID 39136010, 2024). "Bacher investigated the low-avidity CD4+ T cell responses to SARS-CoV-2 in both unexposed individuals and patients with COVID-19." (PMID 38459442, 2024). "Based on CellChat analyses, monocytes communicated predominantly with CD4+ TEM cells positively expressing PTB markers (GBP2, TRAV1-2, and ODF2L) and COVID-19 markers (LAG3 and SLFN5) in both PTB and COVID-19." (PMID 39337460, 2024). "Examining the effects after COVID-19 starting in 2021, further investigation is needed to determine why rural populations in Sughd and DRS face a downward median CD4 count trajectory while Khatlon’s urban population faces a similar decline." (PMID 39066173, 2024). "(I) The proportion of FCGR3A (CD16)-positive cells within the CD4+ and CD8+ T cell populations in BALF from HC and COVID-19 patients, with the FCGR3A expression threshold set at 0.5." (PMID 38607373, 2024). "We focused mainly on CD4+ and CD8+ T- cell epitopes that show immunodominance selectively in SYMP COVID-19 patients infected with various SARS-CoV-2 VOCs." (PMID 38318166, 2024). "We analyzed CD4 + and CD8 + T cell of COVID-19 infected cases between basic immune status and recovery, together with the phenotypic status of T cells." (PMID 38678181, 2024). "We compared the magnitude of CD8+ and CD4+ T- cell responses specific to each of the conserved epitopes from among 38 ASYMP and 172 SYMP COVID-19 patients." (PMID 38318166, 2024). "On multivariable analysis, however, only high expression of CD39+CD45+ (OR 51.4, 95% CI 1.5 to 1763) and TIM3+CD39+CD4+CD3+CD45+ (OR 22.6, 95% CI 1.8 to 277) cells was an independent predictor for severe COVID-19." (PMID 38793691, 2024). "In our study, we characterized CD4+ and CD8+ T cells for their expression of receptors recognizing MIF in order to define the role of this soluble mediator in COVID-19 immunopathology and determine the interplay between these two pathogenic mechanisms." (PMID 37946732, 2023).
COVID-19 (continued). "After the vaccination with mRNA vaccine, spike-reactive CD4+ and CD8+ T cells and plasma antibody neutralization activities were significantly increased in COVID-19 convalescents." (PMID 36444724, 2023). "Previous studies on CD4+ and CD8+ T cells in COVID-19 patients have mostly focused on the progression and prognosis of the disease from mild to severe." (PMID 37799722, 2023). "The results showed that at 6 months post immunization, antibody levels declined, while memory T cells and B cells were comparatively stable, and similar levels of CD4 and CD8 T cell responses were observed between mRNA and protein-based COVID-19 vaccines." (PMID 36961826, 2023). "This is in line with several studies trying to understand the immune profile of COVID-19 patients that report elevated frequencies of CD38+ ICOS+ CXCR5+ CD4+ T cells during acute disease." (PMID 37061513, 2023). "For CD4+ T cells, an increase in frequencies of CXCR2+ CD74+ cells was found in both mild and severe COVID-19 compared to healthy controls (mean: healthy: 17.7%, mild 46.9%, severe 42.9%)." (PMID 37946732, 2023). "Given that all of the uninfected and the majority (87.5%) of the post-COVID-19 individuals were vaccinated with the BNT vaccine, an mRNA-based vaccine that encodes for the full length spike protein, our data indicated that the vaccine could robustly induce CD4+ and CD8+ responses against spike." (PMID 37112825, 2023). "Interaction between innate and adaptive immune responses, as well as B cells, NK cells, CD4 + T cells and CD8 + T cells in the host are critical for the effective antiviral immunity against SARS-CoV-2 (COVID-19) in humans." (PMID 38022818, 2023). "This study aimed to fill this gap by comparing the humoral immune response induced by the inactivated COVID-19 vaccine between PLWH and HNCs, and determining the impact of CD4 cell count on vaccine response in PLWH." (PMID 36670363, 2023). "It is of interest to note that even with the decreased counts of CD4+ and CD8+ T cells, their status was hyperactivated in COVID-19 patients." (PMID 38143504, 2023). "Activation of αβ CD4+ and CD8+ T cells and γδ T cells was similar between placentae from unexposed and COVID-19 pregnancies." (PMID 37036008, 2023). "Several works have reported heterogeneous T cell response in diabetic patients with COVID-19; some revealed significantly lower CD3+, CD4+, and CD8+ T cells, while others revealed decreased CD4+ T cells and increased CD8+ T cells in diabetics." (PMID 38004749, 2023). "We note that several studies reported the significant decrease in CD4+ T cells, CD8+ T cells of COVID-19 patients with increasing disease severity." (PMID 37799722, 2023). "When compared to HIV-1 uninfected healthy persons, the percentage of lymphocytes positive for CD4 was lower in HIV-1 uninfected NC (p ≤ 0.03) and more so in COVID-19 patients (p < 0.0001)." (PMID 36635274, 2023). "The immunophenotyping analysis indicated that patients with moderate–severe forms of COVID-19 had a significantly reduced population of T lymphocytes, CD4+ T cells, CD8+ T cells (only numeric), CD4+/CD8+ index, B lymphocytes, and natural killer (NK) cells." (PMID 37046564, 2023). "We found that IL-10 expression by CD4+ T cells was higher in BAL and blood of severe COVID-19 patients." (PMID 37523305, 2023). "With this understanding, we focused on eight T cell subsets of the total 17 cell types identified, which include activated CD4+ T, CD8+ TCM, CD8+ TEM, CD4+ TCM, naive CD4+/CD8+ T, NK T, Th1, and Th2, across healthy, COVID-19 positive, and recovered cohorts." (PMID 37886355, 2023). "Mild cases (COVID-19 and bacterial non severe sepsis) showed significant differences in the expression levels of CD8 naïve T cells, CD4 naïve T cells, and CD4 memory T cells." (PMID 36979757, 2023).
COVID-19 (continued). "Recently, a decline in CD8+ T cells and CD4+ T cells and an increase in CD16+ monocytes has been observed in COVID-19 convalescent patients even after 6 to 8 months of recovery from the infection." (PMID 37903443, 2023). "The absolute number of CD4 and CD8 T cells was decreased within all of the studied COVID-19 patients compared to healthy individuals." (PMID 36752852, 2023). "COVID-19 is characterized by a decreased number of CD8+ and CD4+ T cells in the blood and in lung tissue, and the severity of the disease is directly related to the lymphocytopenia grade." (PMID 37762093, 2023). "According to the findings of this study, there is a correlation between CD4+ and CD8+ cell counts and ALC in COVID-19 patients." (PMID 37377785, 2023). "Secondary endpoints included geometric mean fold rise (GMFR) in antibody titres; incidence of solicited local and systemic adverse events; IFNγ+ CD4+ and IFNγ+ CD8+ T-cell responses at days 7 and 28; and incidence of COVID-19." (PMID 37549680, 2023). "Among the lymphocytes, CD3+ T cells, CD4+ T cells, CD8+ T cells, and natural killer cells have been shown to significantly decrease in patients with COVID-19." (PMID 37112998, 2023). "So, enrichment of ER stress and apoptosis pathways together in activated CD4+ T and CD8+ T cell populations of COVID-19 patients’ points toward the hyperactivated and dysregulated T cell specific response during the disease phase." (PMID 37886355, 2023). "In addition, severe COVID-19 causes an increase in proinflammatory mediators, such as IL-1, IL-6, and tumor necrosis factor-alpha (TNF-α), less CD4 interferon-gamma (INF-γ) expression, and fewer CD4 and CD8 cells, which enhance susceptibility to both bacterial and fungal infections inside the body." (PMID 36992139, 2023). "Here, we leverage such recognition models to track SARS-CoV-2 epitope-specificity in publicly available bulk TCR repertoires of COVID-19 patients and in sorted CD4+ and CD8+ TCR repertoires of newly recruited COVID-19 patients." (PMID 37325653, 2023). "Subset analysis of T cells revealed that those with COVID-19 had decreased numbers of both helper T (CD3+ and CD4+) cells and suppressor T (CD3+ and CD8+) cells." (PMID 37754237, 2023). "In contrast to mRNA vaccination, both CD4+ and CD8+ T cell responses against spike were readily observable up to 50 days after symptom onset in COVID-19-recovered persons with relative stability over this time span." (PMID 36860850, 2023). "We found five T cell populations, activated CD4+ T, naive CD4+/CD8+ T, CD4+ TCM, NK T, and Th1 cells, to be significantly increased in COVID-19 positive individuals." (PMID 37886355, 2023). "The percentage of CD4+ and CD8+ T-cells in patients with COVID-19 was much lower than it was in the control group, according to the results of immunophenotyping." (PMID 36984473, 2023). "It was found that total lymphocytes, CD4+ lymphocytes, and CD8+ lymphocytes were significantly reduced in COVID-19 patients and were more severely impaired in severe cases." (PMID 37533853, 2023). "In the following, the subpopulations of CD4+T cells, as well as CD8+ T cells and memory T cell subsets in COVID-19 inflammatory conditions, will be discussed." (PMID 36793739, 2023). "Specifically, in COVID-19, memory B cells, CD8+ T cells, and CD4+ memory resting T cells were negatively correlated with neutrophils." (PMID 37822934, 2023). "A poorer prognosis for COVID-19 has also been observed in HIV patients with a low CD4+ T-cell count nadir, with a threshold CD4+ T-cell count of <200 cells/mm3 established in one of them." (PMID 37515137, 2023). "It was observed that an increase in lymphocytes (CD4 and transiently CD45RARO) resulted in lower CRP levels, perhaps leading to COVID-19 recovery and immune response homeostasis." (PMID 36986336, 2023). "A thorough study of B and T cell populations in COVID-19 patients found a link between increased disease severity and lower numbers of CD8+ and CD4+ T cells." (PMID 37767093, 2023).
COVID-19 (continued). "Nevertheless, limited information is available about the immune response to COVID-19 immunization in PLWH, especially in those with low CD4+ T lymphocyte (CD4 cell) count." (PMID 36670363, 2023). "Consistent with several prior studies, our study also indicated that PLWH < 200 subgroup in cohort 1 (3-month interval) showed a weaker humoral immune response to inactivated COVID-19 vaccination, comparing to PLWH CD4 ≥ 200 subgroup (P < 0.05)." (PMID 36936952, 2023). "The frequency of B and CD4+ T cells was equivalent between the SARS-CoV-2–infected (2R and 3R) and COVID-19–vaccinated groups." (PMID 37490342, 2023). "In conclusion, COVID-19 vaccine booster shots were effective in PLWH, resulting in an increase in the number of CD4+ T-cells, neutralizing antibodies that lasted up to six months, and higher levels of neutralizing antibodies lasting approximately 3 months." (PMID 37376408, 2023). "The analyses for the ISB-S dataset were further stratified by cell type (CD4 vs CD8), separated into ISB-S CD4 and ISB-S CD8 datasets, both of which contain TCR sequences of healthy donors and COVID-19 patients." (PMID 36670287, 2023). "(F) Viral load was measured by RT-qPCR in peripheral blood CD4+ and CD8+ T cells from healthy controls (HC) and COVID-19 patients." (PMID 37523305, 2023). "Moreover, the immunotype that exhibited less CD4+ T cell activation was not directly associated with the severity of the disease, which suggested that during COVID-19, a less vigorous immune response could be associated with a pathology that was less severe." (PMID 36675642, 2023). "Circulating activated CD4 + and CD8 + (Cluster Of Differentiation 4 and 8) T cell and plasmablast levels are also increased in COVID-19." (PMID 38007416, 2023). "The present study aimed to clarify the alterations in CD4+ and CD8+ memory T cells’ compartments in SARS-CoV-2-infected patients, with an emphasis on various comorbidities affecting COVID-19 patients." (PMID 38004749, 2023). "In summary, high levels of both SARS-CoV-2 specific CD4+ and CD8+ T-cell responses was observed in this exploratory population of Ugandans well before the COVID-19 pandemic." (PMID 37585383, 2023). "Nevertheless, current data present potentially diversified patterns of CD4+ and CD8+T cell activation in patients with COVID-19." (PMID 36986364, 2023). "Among them, the expression of CD4 (p < 0.001) in COVID-19 samples was lower than that of control samples, while CASP1 (p = 0.018) and EIF2AK3 (p = 0.012) were higher in COVID-19 samples." (PMID 37228369, 2023). "Previous evidence has shown that lymphocyte subsets significantly reduced, including CD3+T cells, CD4+T cells, and CD8+T cells, B cells, NK cells, and cytokine storms such as CRP are common in COVID-19 patients." (PMID 37799722, 2023). "Here, we investigated the dynamics of spike-specific CD4+ and CD8+ T-cell responses elicited after 2- and 3-dose COVID-19 mRNA vaccination in a cohort of 40 older adults and 50 younger healthcare workers who remained naive to SARS-CoV-2 during this time." (PMID 38035132, 2023). "The percentages of CD4+TEMRA cells were significantly low in the total Omicron-infected patient group and in the vaccinated Omicron COVID-19 patient group compared to the uninfected controls (p < 0.05 in each)." (PMID 37881339, 2023). "Elevated levels of S-specific CD4+ T cells were observed in R029 (>10 CD4+ T cells/μl max response) and R046 (~3 CD4+ T cells/μl max response) immediately following post-HCT BNT162b2 mRNA COVID-19 vaccination (lower plots)." (PMID 36936918, 2023). "On the other hand, mean values (absolute and % counts) of CD3+CD4+, CD16+56+ in COVID-19 patients were significantly higher than in patients with CAP." (PMID 36986336, 2023). "Another study confirmed these findings where blood levels of both CD4+ and CD8+ T cells from severe COVID-19 patients (n = 11) were decreased compared to moderate COVID-19 patients (n = 10)." (PMID 36941580, 2023).